CYP11B2 (cytochrome P450 family 11 subfamily B member 2)
Diseases named in the same sentence as CYP11B2 in open-access papers (continued):
Sharing a sentence is not in itself a finding about the gene and the disease.
ischemic stroke (4 papers, 2013 to 2025). A stroke disorder caused by obstruction of blood flow to the brain, due to thrombotic (local blood clot formation) or embolic (due to a blood clot or other material traveling from another site) event. "The association between aldosterone synthase (CYP11B2) C-344T gene polymorphism and ischemic stroke remains controversial and ambiguous." (PMID 23950878, 2013). "Recently, a variety of studies have focused on the association between CYP11B2 C-344T polymorphism and ischemic stroke." (PMID 23950878, 2013). "The present meta-analysis was therefore designed to derive a more precise estimation of the association between CYP11B2 C-344T polymorphism and ischemic stroke." (PMID 23950878, 2013). "As for ischemic stroke, a variety of epidemiological studies have evaluated the role of CYP11B2 C-344T polymorphism, however, there were apparent discrepancies among the results of these association studies." (PMID 23950878, 2013). "Based on comprehensive searches of Medline, Embase, Web of Science, CNKI and CBM databases, we identified and abstracted outcome data from all articles to evaluate the association between CYP11B2 polymorphism and ischemic stroke." (PMID 23950878, 2013). "The present meta-analysis suggested that CYP11B2 C-344T polymorphism was unlikely contribute to ischemic stroke susceptibility." (PMID 23950878, 2013). "Subgroup analysis of CYP11B2 C-344T polymorphism and ischemic stroke in all genetic models." (PMID 23950878, 2013). "It is likely that CYP11B2 C-344T polymorphism may influence the susceptibility of ischemic stroke." (PMID 23950878, 2013). "Thus, the interactions among gene-gene and gene-environment might play a crucial role in the association between CYP11B2 polymorphism and ischemic stroke susceptibility." (PMID 23950878, 2013). "A clinical trial involving 121 patients with ischemic stroke reports associations between nucleotide polymorphisms in CYP11B2, CYP2E1, and CYP7A1 and the occurrence of ischemic stroke." (PMID 41249771, 2025). "Of these IL-1α, CYP11B2, ESR1 (PVUII), α ADD1, TNF α (G488A), CYP4F2, MDR-1 and t-PA (I/D) were found to be significantly associated with ischemic stroke." (PMID 23505425, 2013). "In conclusion, the present meta-analysis provides evidence that CYP11B2 C-344T polymorphism was unlikely to be associated with genetic susceptibility of ischemic stroke based on the current published studies." (PMID 23950878, 2013).
type 2 diabetes mellitus (4 papers, 2014 to 2023). A type of diabetes mellitus that is characterized by insulin resistance or desensitization and increased blood glucose levels. "In 2014, we reported that the aldosterone synthase (CYP11B2) C-344T variant was markedly associated with type 2 diabetes morbidity." (PMID 32999396, 2020). "In conclusion, this study provides a support that a genetic variant of CYP11B2 gene, C-344T is associated to prevalence of type 2 DM, in other words, the variant might be an independent predictor for the type 2 diabetes." (PMID 24549414, 2014).
atherosclerosis (3 papers, 2012 to 2017). A disease characterized by the build-up of fatty material and calcium deposition in the arterial wall resulting in partial or complete occlusion of the arterial lumen. "Therefore, further studies regarding the association between the CYP11B2 c.-344C>T polymorphism and atherosclerosis progression would be of interest." (PMID 22307319, 2012). "In this study, we investigated the association between the ACE c.2306-117_404 I/D, AGTR1 c.1080*86A>C and CYP11B2 c.-344C>T polymorphisms, within the genes encoding for RAAS proteins, and the extent of atherosclerosis." (PMID 22307319, 2012).
congenital adrenal hyperplasia (3 papers, 2018 to 2024). Congenital adrenal hyperplasia (CAH) is an inherited endocrine disorder caused by a steroidogenic enzyme deficiency that is characterized by adrenal insufficiency and variable degrees of hyper or hypo androgyny manifestations, depending of the type and the severity of the disease. "11β-Hydroxylase deficiency (11OHD) is a common form of congenital adrenal hyperplasia that has been shown to result from inactivating CYP11B1 mutations, and pathogenic CYP11B2/CYP11B1 chimeras contribute to a minority of cases." (PMID 29703198, 2018).
coronary artery disease (3 papers, 2009 to 2013). "The interactions of the CYP11B2 C-344T polymorphism, age, and smoking status were also associated with enhanced risk of coronary artery disease." (PMID 23950878, 2013).
Anxiety (2 papers, 2019 to 2022). Intense feelings of nervousness, tension, or panic often arise in response to interpersonal stresses. "Finally, we assessed the moderating influence of candidate genes whose level of methylation is associated with the Nr3c1 genotype on anxiety-like behavior: Ank3, Avp, Avpr1a, Avpr1b, Bdnf, Cacna1c, Cyp11b1, Cyp11b2, Fkbp5, Hsd11b1, Igf2, Morc1, Nr3c1, Oxt, Oxtr, Pclo, Slc6a4." (PMID 30655507, 2019).
coronary artery atherosclerosis (2 papers, 2012 to 2017). "The association between the CYP11B2 c.-344C>T polymorphism and the extent of coronary atherosclerosis has not been investigated before in patients who had undergone first-time coronary angiography." (PMID 22307319, 2012).
hypercortisolemia (2 papers, 2017 to 2021). "CYP11B2 hypomethylation in APAs with parallel hypercortisolemia was unchanged; however, these tumors also presented CYP11B1 promoter hypomethylation, especially at two CpG sites near the Ad1/cAMP response element binding site." (PMID 34771744, 2021). "However, in hypercortisolemia, the role of DNA methylation of 11β-hydroxylase (CYP11B1), which catalyzes cortisol biosynthesis and is highly homologous to CYP11B2, is unclear." (PMID 28894201, 2017).
hyperphosphatemia (2 papers, 2017 to 2022). Abnormally high level of phosphate in the blood. "Together, these findings suggest that hyperphosphatemia increases vascular CYP11B2 transcription, which is a prerequisite for VSMC osteo-/chondrogenic transformation." (PMID 28515448, 2017). "Vascular CYP11B2 may contribute to stimulation of VSMCs osteo-/chondrogenic transformation during hyperphosphatemia." (PMID 28515448, 2017).
kidney failure (2 papers, 2017). An acute or chronic condition that is characterized by the inability of the kidneys to adequately filter the blood. "Vascular CYP11B2 was similarly up-regulated in hyperphosphatemic kl/kl mice, and in the subtotal nephrectomy renal failure mouse model." (PMID 28515448, 2017). "Vascular CYP11B2 was further increased in patients with early stages of renal failure, but the results in brain dead multi organ donors should be interpreted with caution." (PMID 28515448, 2017).
left ventricular hypertrophy (2 papers, 2020 to 2021). Enlargement of the LEFT VENTRICLE of the heart. "Association of response to HT treatment with CYP11B2 polymorphism was also demonstrated in the SILVHIA (Swedish Irbesartan Left Ventricular Hypertrophy Investigation Versus Atenolol) study." (PMID 32443509, 2020). "In addition, CYP11B2 -344C/T polymorphism and -344T alleles were also found to be associated with left ventricular hypertrophy." (PMID 33761712, 2021).
myocardial ischemia (2 papers, 2019 to 2023). A disorder of cardiac function caused by insufficient blood flow to the muscle tissue of the heart. "Results of these studies show that hypoxia is involved in cerebral edema, tumorigenesis, myocardial ischemia and some genes including Endothelin 1 (EDN1), Erythropoietin (EPO) and Aldosterone synthase (CYP11B2) are reported as the key genes of hypoxia adaptation." (PMID 37735456, 2023).
Adrenal insufficiency (1 paper, 2025). Insufficient production of steroid hormones (primarily cortisol) by the adrenal glands. "Our patient did have normal renin and aldosterone levels after developing adrenal insufficiency, likely related to the lower affinity of the osilodrostat for the CYP11B2 enzymatic blockade than for the CYP11B1 enzyme." (PMID 40303510, 2025).
adrenogenital syndrome (1 paper, 2021). Abnormal sex differentiation or congenital disorders of sex development caused by abnormal levels of steroid hormones expressed by the gonads or the adrenal glands, such as in congenital adrenal hyperplasia and adrenal cortex neoplasms. "Pathogenic variants in aldosterone synthase (CYP11B2) were ruled out by Sanger sequencing, as were other forms of adrenogenital syndrome." (PMID 33768328, 2021).
adrenoleukodystrophy (1 paper, 2023). A peroxisomal disorder resulting in cerebral demyelination, axonal dysfunction in the spinal cord leading to spastic paraplegia, adrenal insufficiency and in some cases testicular insufficiency. "Further testing included very long chain fatty acids to exclude adrenoleukodystrophy, the CYP11B2 gene (aldosterone synthase), and an MRI to screen for other morphological abnormalities." (PMID 38075942, 2023).
aldosteronomas (1 paper, 2022). "Aldosteronoma was defined as a well circumscribed CYP11B2-positive solitary neoplasm (≥ 10 mm diameter) composed of clear or compact eosinophilic cells or both cell types." (PMID 35813615, 2022).
Glycogen storage disease type 0 (1 paper, 2022).
hypertrophic cardiomyopathy (1 paper, 2021). A condition in which the myocardium is hypertrophied without an obvious cause. "A close association between low DNA methylation and increased CYP11B2 expression are seen in the hearts of patients with hypertrophic cardiomyopathy." (PMID 33925539, 2021). "Aldosterone production and CYP11B2 gene expression have been shown to be upregulated in cardiac tissues during hypertrophic cardiomyopathy (HCM), and these are recognized as one of the major modifiers of the HCM phenotype." (PMID 33925539, 2021).
hyperuricemia (1 paper, 2023). An abnormally high level of uric acid. "Compared with the control mice, the mRNA levels of enzymes such as cytochrome P450 family 11 Subfamily a member 1 (CYP11A1), 11β-hydroxylase (CYP11B1), aldosterone synthase (CYP11B2) and 3β-hydroxysteroid dehydrogenase 1 (HSD3B1) were significantly lower in the adrenal of hyperuricemia mice." (PMID 38034015, 2023).
melanoma (1 paper, 2020). A malignant, usually aggressive tumor composed of atypical, neoplastic melanocytes. "Human melanoma tissues represented a prominent steroidogenic tumor type, expressing CYP11A1, HSD3B1, HSD3B2, CYP17A1, CYP21A1, and CYP11B1 and not expressing CYP11B2." (PMID 32680985, 2020).
prostate carcinoma (1 paper, 2023). A carcinoma that arises from epithelial cells of the prostate gland. "Further studies in larger cohorts of different racial groups are needed to establish the causal relationship between the SNPs observed in CYP11B2-encoding genes, corticosterone–aldosterone conversion, and prostate cancer risk." (PMID 36837903, 2023). "Exome sequencing analyses of a subset of AA and EA men revealed that AA men with prostate cancer had a significantly higher frequency of multiple SNPs in the genes encoding CYP11B1 and CYP11B2." (PMID 36837903, 2023).
steatosis (1 paper, 2025). Increased lipid within the cytoplasm of cells. "Furthermore, genetic deletion of aldosterone synthase (CYP11B2) in mice conferred resistance to diet-induced hepatic steatosis, indicating that local aldosterone production may play a functional role in liver pathology under metabolic stress conditions." (PMID 40868048, 2025).
tumor (48 papers, 2016 to 2026). "Concurringly, APAs harbouring PRKACA mutations often lack CYP11B2 expression, suggesting a limited role for this mutation in aldosterone synthesis but a potential contribution to tumour formation." (PMID 40725432, 2025). "Aldosterone synthase (CYP11B2)/cortisol synthase (CYP11B1) immunostaining profiles represent a hallmark of the modern approach regarding unilateral tumours with aldosterone and/or cortisol excess." (PMID 36428832, 2022). "Individuals with positive immunostaining for CYP11B1 correlated with wild-type KCNJ5 (p = 0.018), respective CYP11B2 positive was more often found in tumours with KCNJ5 mutation (p = 0.007)." (PMID 36428832, 2022). "Of note, HSD3B1 immunoreactivity was correlated with CYP11B2 in the tumor area, and higher mRNA levels in KCNJ5-mutated APAs than wild type." (PMID 33802814, 2021). "Unique histologic characteristics of adrenals from patients with PA require special attention to tumor CYP11B2 expression for accurate somatic mutation identification." (PMID 34267727, 2021). "A recent study demonstrated a better mutation detection rate using CYP11B2-IHC guided sequencing (94%) as compared to the authors’ previous use of conventional tumor tissue approaches (71%)." (PMID 34267727, 2021). "Targeting the entire coding region for sequencing of genes mutated in APAs based on the tumor expression of CYP11B2, required for the final steps of aldosterone production, provides more accurate determination of the APA-related somatic mutations than the conventional mutation hot spot sequencing." (PMID 36051386, 2022). "Ca2+ channel depolarization, increased Ca2+ signaling, and increased aldosterone production.Heterogeneous expression of CYP11B2 within the tumor tissue; CACNA1H variant detected only in the CYP11B2-positive region of the tumor." (PMID 41601940, 2026). "A CYP11B2-positive cell population was found in the normal adrenal cortex distant from the tumor and was suggested to be APCC/APM." (PMID 40568364, 2025). "In postoperative histopathology findings, an aldosterone-producing cell cluster (APCC)/aldosterone-producing micronodule (APM), stained by CYP11B2 antibody, was found separate from the tumor area." (PMID 40568364, 2025). "The tumours were generally small and demonstrated strong CYP11B2 staining with histological features consistent with a ZG-like APA phenotype." (PMID 40725432, 2025). "Tumour tissue from these patients showed dense CYP11B2 expression, localized to compact, lipid-poor cells." (PMID 40725432, 2025). "As CYP11B2 expression is negatively correlated with tumor size, due to its high affinity for CYP11B2, 11C-MTO PET-CT has been reported to be particularly effective in identifying smaller functional APA." (PMID 40690719, 2025). "IHC revealed diffuse immunoreactivity of CYP11B2 in tumor cells suggestive of neoplastic production of aldosterone." (PMID 38505749, 2024). "qPCR revealed high tumor expression of CYP11B2 mRNA (599-fold over adjacent normal adrenal), confirming accurate sample collection." (PMID 38505749, 2024). "A recent study investigating intra-tumor heterogeneity in APA demonstrated that β-catenin was activated mainly in CYP11B2-expressing regions of the tumor." (PMID 38505749, 2024). "In tumor cells, the positive immunostaining of the cytochrome P450 enzyme CYP11B2, also known as aldosterone synthase, can be used to distinguish APA from NAA." (PMID 38136014, 2023). "The results showed that CYP11B1 (encoding 11β-hydroxylase), CYP11B2 (encoding aldosterone synthase), and Ca metabolism-related receptors (CaSR, VD3R, and PTH1R) were positively expressed in the same region of tumor tissue." (PMID 35960046, 2022). "In APA cases we evaluated p16, p21 and CYP11B2 status in the total area of the tumor and particularly focused on intratumoral histological heterogeneity of tumor cells (clear and compact)." (PMID 34070051, 2021).
tumor (continued). "Our results showed that the tumor area and CYP11B2 H-score were significantly higher in the abnormal staining group than those in the wild-type group." (PMID 34631800, 2021). "The H-score of CYP11B2 adjusted for tumor area was positively correlated with serum aldosterone (r = 0.399, p = 0.000) and ARR (r = 0.301, p = 0.001), and inversely correlated with serum potassium (r = −0.236, p = 0.010)." (PMID 34631800, 2021). "Second, a more targeted method of capturing CYP11B2-expressing tumor cells followed by sequencing was recently proposed, which increased the frequency of CACNA1D and ATP1A1 somatic mutations." (PMID 34572353, 2021). "We then explored the ‘intratumoral heterogeneity’ of cell senescence in APA by further studying CYP11B2 and p16-p21 status in clear and compact tumor cells circumscribed with care in the micrographic images." (PMID 34070051, 2021). "The immunohistochemical results clearly demonstrated the presence of parenchymal cells co-expressing (P)RR and CYP11B2 in the tumor lesion of APA." (PMID 33061968, 2020). "The present study demonstrated that, similar to the results of a previous study, both PACs and urinary aldosterone excretion correlated significantly with immunohistochemical intensity of CYP11B2 multiplied by tumor area." (PMID 33061968, 2020). "By CYP11B2 mRNA expression, CYP11B2 protein expression, and direct measurement of aldosterone in tumor tissue, we confirmed the ability for aldosterone production." (PMID 26815163, 2016). "Furthermore, we extracted total RNA from tumor tissue and evaluated it by quantitative reverse transcription PCR (qRT-PCR) and found that the expression level of CYP11B2 was lower than typical APAs (n = 6) and comparable to typical CPAs (n = 5)." (PMID 40568364, 2025). "In addition, WT tumors tended to harbor higher CYP11B2 status (p = 0.060) and lower tumor size (p = 0.002)." (PMID 34070051, 2021). "Therefore, the functional significance of CYP11B2/1 immunostaining was investigated by correlating the H-score adjusted for tumor area with the endocrine data." (PMID 34631800, 2021). "Recent studies have demonstrated that both CYP11B2 expression in the tumor and tumor size contribute to the overproduction of aldosterone in APA, and CYP11B2 immunohistochemical staining is thus considered a useful histopathological tool to confirm excessive aldosterone production." (PMID 33061968, 2020). "CYP11B2 expression was heterogeneously immunolocalized throughout the tumor area." (PMID 33061968, 2020). "CYP11B2 (aldosterone synthase) expression per tumour area by immunohistochemistry has been reported as higher in micro-APAs compared with macro-APAs together with a higher reported capacity for aldosterone production per tumour area." (PMID 30654107, 2019). "Furthermore, a study investigating CYP11B2 expression in tumor tissue from 51 patients with APAs suggested that tumorigenesis in APAs can occur within preexisting nodules through the acquisition of somatic mutations, possibly via a two-step process." (PMID 30456751, 2018). "For the laboratories using traditional material, i.e., DNA/RNA from macro-dissected snap frozen tumor pieces, confirmation of CYP11B2 mRNA expression by quantitative reverse transcription polymerase chain reaction (RT-qPCR) prior to sequencing could also improve the mutation detection rate." (PMID 34267727, 2021). "In the fifteen tumours subjected to RNA-Sequencing in this study, opposite patterns of expression in tumours with mutations in KCNJ5 and those with mutations in CACNA1D/ATP1A1/ATP2B3 were observed, with KCNJ5-mutants showing higher levels of CYP11B1 expression and lower levels of CYP11B2 expression." (PMID 31000732, 2019). "However, later studies reported distinct expression profiles of APA with KCNJ5 mutations compared with APA without KCNJ5 mutations (with higher CYP11B2 expression in the tumours with KCNJ5 mutations)." (PMID 29642543, 2018).